CD4 (CD4 molecule)
Diseases named in the same sentence as CD4 in open-access papers (continued):
Sharing a sentence is not in itself a finding about the gene and the disease.
infection (continued). "The frequency of total GFP+ cells in the pseudotyped HIVNL-E infection was around 1% with only a few positive cells being detectable in the resting naïve CD4+T cell fraction (representative of several donors at 11 days post infection)." (PMID 27990142, 2016). "CD4+ T cells also mediate direct and indirect viral clearance, and symptom severity reduction in secondary infection." (PMID 27402904, 2016). "In general, the percentage of CCR2, CCR5, CXCR6 and CD11c (Itgax) in live CD4+ or CD4- (putative CD8+) T cells peaked 10 days after infection, when in most cases their total frequency was significantly higher than in the control group." (PMID 27272720, 2016). "Although infection led to significant changes in the phenotype of both CD38+ and CD38- CD4+ T cell subsets during infection, there was a marked increase in CD45RA expression and decrease in Ki67 expression within CD38+ but not CD38- CD4+ T cells." (PMID 27662621, 2016). "The rationale for the use of CsA during primary HIV infection was to decrease the heightened state of T cell activation observed in order to limit infection, and thus depletion, of CD4+ T lymphocytes, contributing to a better long-term preservation." (PMID 27625700, 2016). "On the other hand, during acute and early infection, resting CD4 T cells are frequent targets of infection, constituting up to 90 % of viral RNA+ cells in both HIV-1 infected humans and SIV infected macaques." (PMID 26728316, 2016). "CD4+ T cells obtained from the lungs of mice 18–20 days after infection were stimulated with ESAT6 peptide or anti-CD3/28 mAb." (PMID 26967901, 2016). "Previously, we reported that Tetherin-mediated inhibition of Friend retrovirus (FV) replication at 2 weeks post-infection correlated with stronger natural killer, CD4+ T and CD8+ T cell responses." (PMID 26846717, 2016). "To further probe potential mechanisms driving HAMB-enhanced productive infection of CD4 T cells with a CCR5-tropic virus, we next evaluated the expression of the HIV-1 co-receptors CCR5 and CD4 on LP CD4 T cells following bacterial exposure." (PMID 26762145, 2016). "To explore the antigen location in different tissues during infection, we primarily determined the viruses, CD4+ cell and CD8α+ cell locations by IHC staining assays." (PMID 27150912, 2016). "Though EBNA2 is highly expressed within the first 2 days post-infection, CD4+ T cell recognition of this protein is essentially undetectable at such early times and appears only gradually thereafter." (PMID 27096949, 2016). "Irrespective of tissue origin, ICOS was expressed at significantly higher levels on infection-induced CD4+ YFP+ GFP+ T cells than on the corresponding CD4+ YFP+ GFP− T cells." (PMID 26459508, 2016). "In contrast, in the endocervix, pDCs are recruited to the site of infection where type I IFNs induce pDC production of CCR5 ligands that recruit CD4+ T cells." (PMID 27500281, 2016). "We observed miR-155 and -182 to be significantly up-regulated in Cm infected cultured murine DC, and in Ag-specific murine CD4+ T-cells isolated at day 12 post infection, respectively." (PMID 27556515, 2016). "After 14 weeks post-infection, we observed significant depletion of CD4+ T cells in bone marrow, blood and spleen." (PMID 26996968, 2016). "Preventing transfer and dissemination of HIV-1 to CD4+ T cells has important implications for both early and late infection events." (PMID 26858771, 2016). "Infection resolution began prior to the end of CD4+ T cell depletion in IFN-γ−/− mice, indicating that other mediators must be involved in addition to IFN-γ." (PMID 27600502, 2016). "Efficient infection of CD4+ T-cells occurs via polarized budding of virions or via cell surface transfer of viral biofilms at a tight, specialized cell-cell contact, the virological synapse (VS)." (PMID 27776189, 2016). "FACS analysis of the CNS tissue 9 days post-infection demonstrated a cellular infiltrate constituted mainly by CD4+ and CD8+ T cells." (PMID 27334012, 2016).
infection (continued). "We found the loss of CCR5 interaction resulted in a significant reduction of bystander CD4 T cells death during R3A-5/6AA infection, whereas stimulation of CCR5 with MIP1-β increased bystander pathogenesis induced by R3A-5/6AA." (PMID 27026376, 2016). "HIV-1 can infect CD4 T cells to generate infected cells (CH) at a rate proportional to the concentrations of HIV-1 and CD4 T cells, via the infection rate constant (k5)." (PMID 27010978, 2016). "Negatively selected CD4+ T cells from WT and ΔdblGATA brains after 1 and 2 wks of infection were compared at the transcript level for Il4 and Gata3 (a transcription factor involved in polarizing T cells towards Th2 phenotype) expression." (PMID 27332553, 2016). "These limitations prevented the establishment of a correlation between the prevalence of particular infection agent and the exact CD4+ cell count, or antemortem examination outcomes." (PMID 27611681, 2016). "Infection by Candida is observed with any level of CD4 Tcells, such that the reduction in these cells influences only its frequency andseverity." (PMID 27384466, 2016). "Conversely, the infection of PBMC with a strain of M. bovis BCG unable to produce mature lipoproteins resulted in significantly reduced HIV infectivity of CD4+ T cells." (PMID 26807859, 2016). "Efficient infection of CD4+ T-cells requires cell-cell contacts while cell-free virus transmission is inefficient." (PMID 27005656, 2016). "We provide the first evidence in relevant infection models that shows CCR5 interaction with a dual-tropic HIV-1 Env played a significant role in Env-induced depletion of CD4 T cells." (PMID 27026376, 2016). "ART initiation during the first year of infection efficiently decreased plasma viral load to undetectable levels in all individuals and increased CD4 counts." (PMID 27553844, 2016). "In single round infection assays using virions produced by CD4+ T-cells (normalized to p24), MA1671 partially rescued infectivity of the autologous C-Env1671 strain, (from 12.6% to 45.5%) but did not rescue infectivity of any other subtype C Env." (PMID 27598717, 2016). "Here we show that IFN-γ accounts for only ~30% of the cumulative CD4 T cell-mediated reduction in lung bacterial loads over the first 1.5 months of infection." (PMID 27244558, 2016). "We show how we can lower bacterial burden and inflammation at the site of infection by enhancing either CD4+ or CD8+ T cell proliferation in the lymph node early on during infection (i.e., within the first 2 months)." (PMID 28989808, 2016). "This indicates that memory Ag-experienced CD4+YFP+GFP− T cells are predisposed and programmed toward rapid induction of IL-10 following reactivation during secondary infection." (PMID 27630165, 2016). "We have previously shown that HSV-2 vaginally infected macaques are more susceptible to SHIVSF162P3 infection in vivo and this correlates with an HSV-2-driven increase in the expression of α4β7 on CD4+ T cells ex vivo." (PMID 26886938, 2016). "Evidence from mouse models and experimental human infections suggests that both CD4+ and CD8+ T cells play an important role in protective immunity to P. falciparum malaria." (PMID 27165269, 2016). "Compared to mock infection, we observed a significant higher percentage of dying cells in the p24(−) CD4 T cell populations at 6 days post R3A infection, therefore we termed it as bystander cell pathogenesis." (PMID 27026376, 2016). "During the acute stage of infection there is wide viral dissemination to many cell and tissue types, a high plasma viral load, a decrease in CD4+ T cells and an inverted CD4:CD8 ratio in the peripheral blood." (PMID 26741651, 2016). "We calculated the contribution of cells expressing PD-1, TIGIT or LAG-3 to the total reservoir by taking into account the frequency of these subsets within the CD4 compartment and their relative infection frequencies." (PMID 27415008, 2016).
infection (continued). "Because the majority of human chlamydial genital infections are without signs or symptoms, suggesting mild inflammation, perhaps this mild inflammatory response results in incomplete or ineffective priming of the genital tract by CD4 T+ cells during infection." (PMID 27600502, 2016). "One single administration of 1 mg depleting Ab immediately before infection resulted in 70% depletion of CD4+Foxp3+ Tregs in the blood at steady state and following infection." (PMID 26286232, 2016). "A common feature in acute-infection models is the severe atrophy of the thymus, mainly due to apoptosis related depletion of CD4+CD8+ thymocytes, the major cellular type in the organ." (PMID 27736987, 2016). "There was a higher frequency of CD38+ CD4+ T cells but not CD38+ CD8+ T cells or B cells, and absolute numbers of CD38+ CD4+ T cells and B cells also increased in the peripheral blood during infection." (PMID 27662621, 2016). "Here we show that IFN-γ accounts for only ~30% of CD4 T cell-dependent cumulative bacterial control in the lungs over the first six weeks of infection, but >80% of control in the spleen." (PMID 27244558, 2016). "We also observed a down-regulation of the antigen processing function of CD4+MHC class II− pDC following infection with FMDV A24 Cruzeiro." (PMID 27008425, 2016). "To define the specific pathways downstream of the chemokine receptor important for HIV integration, we next tested inhibitors of p38, MEK1/ERK1/2, JNK, AP-1 and NF-κB, prior to infection of CCL19-treated resting CD4+ T cells." (PMID 27459960, 2016). "A statistically significant decline in the antigen processing ability of CD11c+ cDC, CD11c− cDC, and CD4+ pDC was observed at 1 day post-infection, and this returned back to baseline levels by day 2 to 3 after infection." (PMID 27008425, 2016). "During the evolution of the infection, the number of IL-10-producing CD4+ T-cells decreased in both infections." (PMID 27073297, 2016). "First we examined their potential to modulate HIV-1 cis-infection of CD4+ enriched T-cell blasts (CD8+ depleted T-cell blasts)." (PMID 26808476, 2016). "To compare the ability of CD38+ and CD38- CD4+ T cells to produce IFN-γ, we assessed the frequency of IFN-γ positive cells induced by mitogenic stimulation in CD38+ and CD38- CD4+ T cell populations collected prior to and at peak infection seven days later." (PMID 27662621, 2016). "DC-SIGN, thus, allows DCs to carry HIV-1 to the lymph nodes where interactions between DCs and T cells leads to transmission of the virus to CD4+ T cells, leading to their infection and eventual depletion." (PMID 28066413, 2016). "These ‘depleters’ were used to compare the ability of different HAMB species to enhance LP CD4 T cell infection and depletion." (PMID 26762145, 2016). "When the mAb treatment started at 8 weeks post-infection, numbers of CD4 T cells, B cells, DCs and eosinophils also remained significantly lower in those animals compared to control mice at 12 weeks post-infection." (PMID 27690127, 2016). "This was done by isolating memory CD4+ T cells from previously infected mice and then reinfusing them into animals that had resolved the same type of infection." (PMID 27160938, 2016). "In this model, infection of Indian RMs with SIVsab, the virus that naturally infects AGMs in West Africa, results in a robust acute viral replication and a massive CD4+ T cell depletion." (PMID 26858716, 2016). "Unexpectedly, IFN-γ production was significantly impaired in the CD38+ CD4+ T cell subset both prior to and during infection (p = 0.031 and p = 0.031)." (PMID 27662621, 2016). "C3H/HeN mice depleted of CD4+ T cells underwent a comparable course of disease in a sublethal infection with R. conorii as control mice." (PMID 27875529, 2016). "Previously, we reported that CD4+ T cell hypo-responsiveness in the sdLN observed after repeated infection is dependent on IL-10." (PMID 27505056, 2016).
infection (continued). "Accordingly, the rationale behind this possible approach is that moving infection toward the inoculated cells should prevent infection and depletion of the patient’s own CD4+ T cells and, therefore, AIDS." (PMID 27128948, 2016). "As expected, older adults had a longer duration of infection (median 8.3 years versus 1.2 years, p = 0.005), and a subsequent lower nadir CD4+ T lymphocyte count (median 109 versus 298 cells/mm3, p = 0.020)." (PMID 27273074, 2016). "In particular, we used single-cell RNA-seq data from a model of CD4+ T cells purified from PcAS PbTII-infected mice at 2, 3 and 4 days post-infection." (PMID 27176874, 2016). "These early changes in cell-associated HIV-1 DNA levels over the first year of cART likely reflect a reduction in new rounds of infection along with clearance of productively infected CD4+ T cells containing integrated HIV-1 DNA." (PMID 27104621, 2016). "So far, a protective function of CD4+ T cells has only been demonstrated in the infection of mice with SFG Rickettsiae." (PMID 27875529, 2016). "Full CD4 T cell differentiation then occurs at sites of infection and inflammation after they have migrated from the secondary lymphoid organs." (PMID 27280403, 2016). "CD4+ T cells that produce IFN-γ are the source of host-protective IL-10 during primary infection with a number of different pathogens, including Plasmodium spp." (PMID 27630165, 2016). "Both CD103+ and CD11b+ DCs activate naïve CD4 T cells, drive T helper 1 (Th1) responses, and generate effective memory T cell populations to protect against subsequent infections." (PMID 26965109, 2016). "The 1.3 log10 lower viral set point in HLA-B*58:02–positive vaccinees and the inability of >50% to meet the CD4+ T-cell count criteria for ART initiation by 600 days after infection are consistent with vaccine-mediated protection against rapid progression." (PMID 26951820, 2016). "As with infection, antigen-specific CD4 T cell reactivity to HA and NP epitopes was assayed from Tfh and NonTfh populations derived from the draining LN of vaccinated mice." (PMID 27329272, 2016). "In a preliminary experiment, we observed, in the peak of infection at 44 days post-infection, an induction of CD4+ IFN-γ+ T cells by intranasal LaAg vaccine in comparison to PBS in popliteal lymph node cells." (PMID 27716449, 2016). "In the studies presented here we evaluated the susceptibility of macrophages and dendritic cells (DCs) to YFV infection, their cytokine response to infection and their ability to interact with and stimulate CD4+ T cells." (PMID 27191161, 2016). "Adapted from the JC.53 parental HeLa cell line—which expresses high levels of CD4 and CCR5—TZM-bl cells are susceptible to infection by a wide variety of HIV-1 isolates." (PMID 27775563, 2016). "Our results demonstrate that Vpx is critically important for countering SAMHD1 during SIVmac infections of memory CD4+ T lymphocytes both in vitro and in vivo." (PMID 25996507, 2015). "The sum of these data suggest a novel role for human CD4+CD25+Foxp3+ cells in protection against infection and identify a new molecule, D4GDI, through which such protection is mediated." (PMID 25659138, 2015). "T-bet-expressing CD4+ T cells, representing Th1-type T cell immunity, increased in the lungs of mice that were infected with Mtb strains at 14 days post-infection in a time-dependent manner." (PMID 26675186, 2015). "For these studies, mice were depleted of CD4+ by weekly administration of anti-CD4+ antibody or control antibody (rat IgG2b) starting a month prior to infection with WT C. neoformans." (PMID 26322039, 2015). "This elite controller had a CD4 count that averaged 580 cells/μl during the first year of infection." (PMID 25569444, 2015). "These included two studies of infection of the SupT1 cell line, a study of ex vivo infection of primary CD4+ T cells and a study of lymphatic tissue biopsies from acutely viremic patients." (PMID 26377088, 2015).
infection (continued). "Under the assumption that cART was initiated when the CD4 count dropped below 350 cells/mm3, the mean time spent from infection to treatment initiation was 5.2 years." (PMID 25901355, 2015). "Nevertheless, myeloid cells can contribute to HIV-1 dissemination through the alternative pathway of trans-infection of CD4+ T cells." (PMID 25947229, 2015). "HIV is a neurotropic virus that invades the central nervous system (CNS) early after infection, primarily via infected monocytes/macrophages and CD4+ lymphocytes." (PMID 28596857, 2015). "The lungs of 38 Indian rhesus macaques in early to later stages of SIVmac251 infection were examined, and the numbers of CD4+ T cells and macrophages plus the frequency of SIV RNA+ cells were quantified." (PMID 25933119, 2015). "Following the clearance of acute LCMV infection and the corresponding contraction of virus-specific CD4 T cells, both Th1 and Tfh memory subsets are maintained at relatively stable numbers for approximately 60–150 days post-infection." (PMID 25699040, 2015). "In our model, early IL-10 production by dermal CD4+ T cells was important in limiting the extent of inflammation at the site of infection by reducing skin thickening and neutrophil recruitment." (PMID 25974019, 2015). "Using this model we find that hybrid spreading is critical to seed and establish infection, and that cell-to-cell spread and increased CD4+ T cell activation are important for HIV-1 progression." (PMID 25837979, 2015). "During infection, naïve CD4+ T helper cells differentiate into specialized effector subsets based upon environmental signals propagated by the cytokine milieu." (PMID 26500048, 2015). "TB is primarily a pulmonary disease with an immune response dominated by a CD4/Th1/Th17 response early during the infection, and CD8 T cell responses increase as the infection progresses." (PMID 26599077, 2015). "To test if cholinergic regulation of CD4 T cell cytokine responses influenced adaptive immunity, we next examined how this affected the outcome of secondary infection, as this requires a CD4 T cell-driven Th2 immune response in the lung." (PMID 25629518, 2015). "The expression of CD69 significantly decreased during the course of infection (CD4–LCMV—day 14 vs. day 56—**p < 0.01; CD8-LCMV—day 14 vs. day 56—*p < 0.05)." (PMID 26322025, 2015). "Data from 499 HIV-1 seroconverters with frequent (monthly to quarterly) follow-up revealed that CD4:CD8 ratio was stable in the first 3 years of infection, with a modest correlation with VL and CD4 slope." (PMID 26191056, 2015). "In fact, there is a high proportion of missing data in key variables such as CD4 cell counts at baseline, treatment status at enrollment, transmission route of infection, and clinical stage category." (PMID 26425365, 2015). "For instance, infection of CD4 T cells with HIV results in depletion of these lymphocytes because of programmed cell death." (PMID 25880754, 2015). "Median estimated duration of infection was 14.4 years (range 0.4–26.3 years), median CD4 cell count was 643 (range 196–1,740)." (PMID 27917362, 2015). "We used the CD4+ T cell line CEM that responds with IFN-α release upon Vesicular Stomatitis Virus (VSV) infection as monitored by ELISA." (PMID 26375588, 2015). "It has been mainly described that the patients with established chronic HCV infection frequently have much weaker CD4+ T-cell responses specific to HCV antigens than those with resolved infection." (PMID 26213920, 2015). "Another possibility is that infection occurs at a “sweet spot” in the trajectory that activated CD4+ T cells taken from full activation to a fully rested state." (PMID 26067822, 2015). "A decrease in the infection of CD4+ TSCM cells was found to preserve CD4+ T cell homeostasis and prevents disease progression despite significant viremia in both HIV-1 and HTLV-1 infections." (PMID 26462561, 2015).